CAT (catalase)
Diseases named in the same sentence as CAT in open-access papers (continued):
Sharing a sentence is not in itself a finding about the gene and the disease.
type 2 diabetes (continued). "The authors reported low levels of TAC and salivary catalase, while MDA and TOS were significantly higher in patients with type 2 diabetes compared to healthy controls." (PMID 34829612, 2021). "Some studies suggest that in diabetes type 2, a diminished paraoxonase 1 (PON1) activity was seen simultaneously to superoxide dismutase (SOD) decrease and a catalase (CAT) increase." (PMID 32911700, 2020). "The present study investigated the effect of Iranian Propolis on fructosamine, the catalase activity and changes in oxidized LDL level in type II diabetes." (PMID 30858941, 2019). "In type 2 diabetes, the activity of major antioxidant enzymes such as superoxide dismutase (SOD), glutathione peroxidase (GPx) and catalase (CAT) is altered." (PMID 27592002, 2017). "In the study for type 2 diabetes mellitus (T2DM) model mice, Ber could increase the mRNA expression of SOD in the liver and the activities of SOD and CAT in the kidney tissue, which showed that Ber has a role in combating oxidative stress." (PMID 38318145, 2024). "Additionally, simultaneous marked decreases in GST, CAT, GPx, and SOD activities, as well as GSH content, were noticed in rats from the type 2 diabetes model relative to controls (p < 0.01)." (PMID 34834352, 2021). "Of note, however, the men with type 2 diabetes in this study did not exhibit lower catalase protein expression compared to the nondiabetes counterparts." (PMID 33426802, 2021). "They reported that type 2 diabetes obese individuals lack activity in reactions catalyzed by lactate dehydrogenase, catalase and cysteine dioxygenase, comparing to the non-type 2 diabetes obese subjects." (PMID 26696898, 2015).
hepatoma (54 papers, 2008 to 2025). "Mel treatments have also been associated with lower enzymatic activities of SOD and CAT accompanied by an increased level of ROS observed in human colorectal cancer cells and in the hepatocellular carcinoma cells." (PMID 41256015, 2025). "ROS exposure has been shown to downregulate catalase expression in human hepatoma cells, and another study linked low catalase expression to MM cells sensitive to ROS generation by parthenolide treatment." (PMID 37628771, 2023). "Compared with the control condition, treatment with ginger extract at a concentration of 200–500 μg/ml caused a significant reduction in SOD, GPx, and CAT activities in a hepatoma cell line." (PMID 31531114, 2019). "In line with this notion, exposure to H2O2 caused an increase in catalase levels and activity in rat astroglial cells, in human retinal pigment epithelial cells, in hamster tracheal epithelial cells, and in hepatoma cells." (PMID 26881079, 2016). "Moreover, a possible correlation between the rs1001179 SNP in the CAT promoter and susceptibility to disease has been suggested in prostate cancer and hepatocellular carcinoma." (PMID 36112236, 2022). "Others showed that FBP induced oxidative stress in hepatic carcinoma cells, which caused an inhibition in proliferation, and this effect was suppressed when these cells were treated with anti-oxidants, such as N-acetyl-l-cysteine or catalase." (PMID 31509566, 2019). "Peroxisome acyl-CoA oxidase 1 (ACOX1) is the primary catalase enzyme in the peroxisomal β-oxidation pathway, the dysfunctioning of which leads to abnormal lipid metabolism and hepatocellular carcinoma, and potentially results in metabolic disorders." (PMID 40244197, 2025). "The CAT gene rs769217 SNP locus has been reported to correlate with disease risks such as hepatocellular carcinoma, cirrhosis, and glaucoma." (PMID 40433469, 2025). "The polyphenols-loaded nanoparticles significantly decreased the malondialdehyde (MDA) concentration and increased the superoxide dismutase (SOD) and catalase (CAT) activities in peroxide-treated human hepatoma cells (HepG2)." (PMID 36360091, 2022). "A similar observation of higher activity of SOD and CAT were reported in hepatoma (HepG-2) cell lines." (PMID 34393434, 2021). "On the other hand, in other forms of cancer such as hepatoma, a lower level of anti-oxidative enzymes, including catalase, can be found." (PMID 33924068, 2021). "Oxidants such as H2O2 were also reported to double CAT activity of rat hepatoma cells while pretreatment with epicatechin tripled the value." (PMID 27775607, 2016). "The P. krukoffii and P. putumayoense extracts markedly reduced catalase activity in this rat hepatoma cell line (40% and 23% reduction at 24 h, respectively; 45% reduction at 48 h by both Piper species)." (PMID 25558904, 2014). "The rat hepatoma cell line exhibited higher glutathione peroxidase and catalase basal activities than in the human cell lines." (PMID 25558904, 2014). "Another possible explanation for the inhibition of CAT in hepatoma was suggested to stem from the secretion of a toxohormone from neoplastic tissue." (PMID 18950483, 2008). "Sierra-Rivera and co-workers noted that the decline in enzymatic activities of CuZnSOD, MnSOD and catalase in hepatoma was due to a decline in the levels of immunoreactive proteins." (PMID 18950483, 2008). "Another possible explanation was suggested to stem from the secretion of a toxohormone by the cancer cells themselves (observed only in the case of inhibition of catalase in hepatoma)." (PMID 18950483, 2008). "Intracellular zinc ions could produce reactive oxygen species, facilitated by the generated H2S gas from ZnS@BSA via specifically inhibiting catalase in hepatocellular carcinoma cells through activating the cGAS/STING signals in mice." (PMID 40375976, 2025).
hepatoma (continued). "Consequently, the effect of Brassica oleracea extracts on the antioxidant defense system, namely catalase activity, of human hepatoma cells (HepG2) incubated with supraphysiological concentrations of FFAs was also evaluated." (PMID 36839282, 2023). "The results obtained in this study also indicated that treatment with (+)-catechin could significantly increase the expression levels of ESR1 and CAT in human hepatocellular carcinoma cells." (PMID 36193154, 2022). "SOD and CAT activity were found to be higher in hepatoma (HepG-2) cell lines, as well." (PMID 36199748, 2022). "A previous report has also demonstrated that the promoter activity of GBAP1 was negligible through a CAT assay in the epithelial cell lines (HeLa or hepatoma cells) and a B cell line, prepared using a 650-bp SacI fragment, containing the original exon one as the promoter region." (PMID 35831491, 2022). "Notably, catalase mRNA levels also decreased by stimulation with soluble egg products in human hepatoma cells." (PMID 36590323, 2022). "Moreover, the antioxidant peptide from fish skin gelatin hydrolysate increased the expression of cellular antioxidant enzymes (catalase, superoxide dismutase, and glutathione peroxidase) in human hepatoma (Hep3B) cells." (PMID 32906682, 2020). "Suppressed catalase activity has been addressed in hepatoma cells and activated HSCs." (PMID 25816210, 2015). "Mechanisms involved in decreasing catalase activity have been reported in hepatoma cells due to the genomic methylation of CpG sites in the catalase promoter, which might also apply to aHSCs during transformation." (PMID 25816210, 2015). "In addition, HDGF significantly increased catalase protein levels in hepatoma cells." (PMID 37827291, 2023). "Human hepatocellular carcinoma cell lines (HepG2) cells were treated with 0.1 mM oleic acid and HFA (0.125, 0.25 mg/mL), and intracellular TC, TG, HDL-C, SOD, CAT and MDA were measured." (PMID 35990322, 2022). "Relatively high NQO1 and low catalase expression in various HCC patients and cell lines indicates a potent therapeutic window in liver carcinoma for β-lap, and our above data confirmed that β-lap efficiently represses tumor cell growth in vitro." (PMID 34676172, 2021). "AgNPs induced radiation sensitivity by decreasing the levels of catalase (CAT), superoxide dismutase (SOD), and total GSH in human hepatocellular carcinoma HepG2 cells." (PMID 32168899, 2020). "It has been reported that RSV treatment attenuates protein oxidation and improves SOD, GPx, CAT, GST, and GSH levels through the activation of Nrf2 mRNA levels and SIRT1 in diabetic rats and human liver carcinoma cells." (PMID 30987086, 2019). "Human hepatoma HepG2 cells subjected to apigenin accumulated H2O2, which correlated with a decrease of catalase mRNA and catalase activity and led to cell death." (PMID 27911871, 2017). "An antioxidant peptide from skin gelatin hydrolysate of hoki fish increased expression of cellular antioxidant enzymes including catalase (CAT), superoxide dismutase (SOD), and glutathione peroxidase (GPx) in human hepatoma cells (Hep3B)." (PMID 24527452, 2014). "Research now show that CAT, SOD and GSH-Px are strongly down-regulated in Hepatocellular carcinoma, the putative explanation being likely, again, a genetic reprogramming in favor of high proliferative capacity of the cancer cells." (PMID 18950483, 2008).
hepatoma (continued). "GPX1, SOD1, and CAT convert superoxide radicals (O2•−) produced in the mitochondrial respiratory chain into O2 and H2O, while PGLS inhibits the expression of ROS in human hepatocellular carcinoma cells, thereby inducing apoptosis." (PMID 38731375, 2024). "Regarding in vivo studies, the pretreatment with carvacrol in colon cancer and hepatocellular carcinoma increased the levels of enzymatic antioxidants such as GPx, SOD, CAT, GR, and GSH, revealing a chemopreventive effect of carvacrol and prevention of cell proliferation." (PMID 34305611, 2021). "FB1 could induce oxidative stress in hepatocellular carcinoma cell line HepG2 by the increased content of MDA, and the decreased activities of CAT, SOD." (PMID 31269688, 2019). "Catalase overexpression had no clear effects on the expression or transcriptional activity of HIF1 in human hepatoma cells." (PMID 26222311, 2015). "FOXM1 is known to regulate the expression of important AOS genes including catalase, superoxide dismutase 2 (SOD2) and PRDX3 which we found to be highly overexpressed in multiple cancers (group 6), at the exception of catalase, exclusively overexpressed in hepatocellular carcinoma (group 3)." (PMID 24342878, 2013). "Among 50 HBV-related hepatocellular carcinoma (HCC) specimens, 72% of HCCs showed lower catalase levels than those of surrounding non-tumor tissues." (PMID 25361011, 2014). "Whether this applies as well to cell lines in which catalase-negative peroxisomes have been described, like Morris hepatoma, rat FTO-2B hepatoma cells, or HT29 cells (derived from human colon carcinoma), is not known." (PMID 32266253, 2020). "We measured resorufin fluorescence generated with and without HRP, PMSF and catalase from four cell lines: AML12 mouse hepatocytes; MRC5, a primary human fibroblast strain; C2C12 undifferentiated mouse myoblasts; and Hep G2 human hepatocellular carcinoma cells." (PMID 26577176, 2016).
ulcer (54 papers, 2008 to 2026). "A significant increase in CAT activity was seen in rats administered A. eupatoria leaf ethanol extract compared with the ulcer control rats." (PMID 41268097, 2025). "Rats fed with Schiff base compound 50 mg/kg had suggestively greater SOD and CAT standards compared to the rats fed with Schiff base compound 25 mg/kg and ulcer control groups." (PMID 39830532, 2024). "ASX supplementation in various ulcer models yielded increased antioxidant enzyme activities—such as catalase (CAT), superoxide dismutase (SOD), and glutathione peroxidase (GPX)—and decreased lipid peroxidation levels in the ulcer group." (PMID 39458422, 2024). "Since ethanol-induced ulcer is usually associated with production of ROS, this resulted in the consumption of GSH and CAT, lowering their levels in the gastric tissue." (PMID 38276520, 2024). "In gastric tissues, NAC administration decreased the level of lipid peroxidation and activity of catalase, which were increased by induced ulcers." (PMID 38279215, 2024). "The activity of GST, GSH and catalase was significantly reduced while that of LPO increased in ethanol induced ulcer gastric tissues." (PMID 36144661, 2022). "The present study revealed that there were significant increases in lipid peroxidation (MDA) and a reduction in the levels of GSH, GPX, SOD, and catalase in the untreated ulcer group compared with normal control group." (PMID 28250794, 2017). "The various gastric parameters like volume of gastric juice, pH, free and total acidities, ulcer index, and levels of antioxidant enzymes like catalase, superoxide dismutase, and lipid peroxidation marker malondialdehyde were determined." (PMID 24977051, 2014). "weight of the extract significantly increased (p< 0.001) CAT activity from 4.64 ± 0.08 nmol/min/mg protein in the ulcer control to 7.76 ± 0.08 nmol/min/mg protein in CS-1000." (PMID 23228052, 2012). "The ulcer index was calculated together with the determination of catalase and SOD activities and MDA contents." (PMID 22016781, 2011). "There was significant reduction in ulcer index as well as the extent of lipid peroxidation and significant increment in preventive antioxidants like superoxide dismutase, catalase and chain breaking antioxidant reduced glutathione." (PMID 21593966, 2008). "Increased levels of aggressive ulcerogens result in the overproduction of ROS, such as superoxide anions, hydroxyl radicals, and hydrogen peroxide, and the depletion of protective factors, such as antioxidants (SOD, CAT, GSH, etc.), causing gastric mucosal erosion and ulcers." (PMID 33260419, 2020). "The activity of catalase in gastric mucosa significantly varied after ethanol treatment, decreasing from 7.67 ± 0.16 nmol/min/mg protein in the baseline (intact) group to 4.64 ± 0.08 nmol/min/mg protein in the group exposed to ethanol (Ulcer control)." (PMID 23228052, 2012). "Ulcer index measurement as well as malondialdehyde level, superoxide dismutase, catalase and reduced glutathione assays are performed in stomach homogenate of rats with swimming stress induced ulcer after four days rice bran oild (RBO) (1 ml/day) treatment and compared with control animals." (PMID 21593966, 2008). "However, in some ulcer studies, CAT enzyme activity was found to be high in the indomethacin group." (PMID 40746654, 2025). "However, it has been reported that the first line of defense against oxidative damage caused by injury like ulcers involves the migration of free radical scavenging enzymes such as SOD, CAT, and GPx, to eliminate first O2 and H2O2 before forming harmful hydroxyl (OH∙) radical." (PMID 28250794, 2017). "The antioxidant ability was assessed by measuring catalase (CAT), glutathione-S-transferase (GST), glutathione (GSH), superoxide dismutase (SOD), and lipid peroxidation (LPO) levels in both edema and ulcer models." (PMID 41615937, 2026). "Ulcer area, mucin content, and biochemical indicators (GSH, SOD, CAT, GST, MPO, MDA) were evaluated." (PMID 42043715, 2026).
ulcer (continued). "Biochemical analyses revealed reduced TBARS and increased SOD, CAT, and GSH levels in ulcer tissue, indicating enhanced local antioxidant defense." (PMID 41155930, 2025). "Ulcer control rats (B) revealed notably fewer antioxidant (SOD, CAT, and PGE2) activities than those of the reference drug (C) or PAG‐treated rats (D and E)." (PMID 40034223, 2025). "In conclusion, A. eupatoria extract documented gastroprotective influence, reduction in ulcer area, rise in pH, and mucus excretion, increased SOD and CAT, and reduced MDA level." (PMID 41268097, 2025). "Ulcer rats displayed a considerable decline in endogenous enzyme activities related to antioxidants, explicitly SOD and CAT." (PMID 41268097, 2025). "The ulcer control group showed significantly reduced SOD and CAT activities compared to normal group." (PMID 39830532, 2024). "A comprehensive experimental ulcer study examining antioxidant enzyme activities has shown that ASX application increases SOD, CAT, and GPX enzyme activities in a dose-dependent manner." (PMID 39458422, 2024). "In ethanol-induced ulcer stomach tissues, GST, GSH, and catalase levels were decreased, but LPO levels were increased." (PMID 36059979, 2022). "Referring to the ulcer control rats, the ZJP pre-treatment (1, 2 and 4 g/kg) evidently elevated the CAT levels by 71.9, 117.3 and 161.6%, respectively." (PMID 35938492, 2022). "According to our results, ulcer groups showed a significant decrease in rats’ antioxidant system (GSH, CAT, GST and SOD), which is considered the initial defense against ethanol-induced free radical damage to gastric mucosal cells." (PMID 36662198, 2022). "Compared with the ulcer control rats, ZJP (4.0 g/kg) enhanced the antioxidant capacity of gastric tissue: superoxide dismutase (1.33-fold), catalase (2.61-fold), glutathione (2.14-fold), and reduced the malondialdehyde level (0.48-fold)." (PMID 35938492, 2022). "In rats with ethanol-induced ulcers, piperine decreased the ulcer area, increased SOD, CAT and GSH-Px activities, and reduced MDA, ROS and MPO levels." (PMID 36432431, 2022). "Piperine significantly increased SOD, CAT and GSH-Px activities, but decreased the ulcer area, MDA, ROS and MPO levels in the gastric tissues of rats." (PMID 36432431, 2022). "AA caused a significant reduction in body weight and increased macroscopic and microscopic ulcer scores along with a significant decline in antioxidant enzymes, superoxide dismutase (SOD), and catalase and antioxidant substrate, glutathione (GSH)." (PMID 35566122, 2022). "In ulcer-induced group the anti oxidant enzymes SOD, CAT, GPX, LPO and MPO were decreased when compared with control group." (PMID 34393417, 2021). "In the present study, it was found that ethanol-induced ulcer rats showed decreased SOD and CAT levels in gastric mucosa." (PMID 32318292, 2020). "Because of the ethanol insults in ulcer control groups, significant reductions of SOD and CAT activities in comparison with control group were found." (PMID 31889181, 2020). "Resveratrol, a main active component of P. cuspidatum, has been reported to produce gastroprotective and ulcer healing effects in EtOH- and acetic acid-induced ulcer models, respectively, by augmenting SOD, GSH, and CAT levels." (PMID 32727104, 2020). "Plants that contain flavonoids have been reported to increase CAT, GSH and SOD activities in stress-induced ulcers." (PMID 28251024, 2017). "In the ulcer control group, there was a significant decrease in the gastric mucosal GPx, SOD, and CAT activities (50%, 60%, and 28%, resp)." (PMID 28250794, 2017). "In ulcer studies, increased MDA and SOD values, and decreased CAT, GSH and GSH-Px values or decreased MDA and SOD values, and increased CAT, GSH and GSH-Px values have been reported." (PMID 28251024, 2017).